SCIN (scinderin)
Diseases named in the same sentence as SCIN in open-access papers (continued):
Sharing a sentence is not in itself a finding about the gene and the disease.
head and neck tumors (1 paper, 2013). "SCINDERIN is weakly expressed by head and neck tumors, as only 9 out of 83 patients expressed this biomarker." (PMID 24330498, 2013).
SCIN also shares sentences with these, for which no sentence is quoted: acute myeloid leukemia (1 paper); adenoma (1); anaplastic astrocytoma (1); diffuse astrocytoma (1); Hemoptysis (1); intestinal diseases (1); leukopenia (1); lung carcinoma (1); nasopharyngeal carcinoma (1); oligodendroglioma (1); prostate tumor (1); thymoma (1).